GJB6 (gap junction protein beta 6)
Description:
One gap junction consists of a cluster of closely packed pairs of transmembrane channels, the connexons, through which materials of low MW diffuse from one cell to a neighboring cell.
Synonyms: Cx30; EDH; HED; DFNA3; DFNA3B; DFNB1B; ECTD2; ED2; HED2
Tractability: Antibody: UniProt places it where antibodies can reach, with medium confidence; UniProt predicts a signal peptide or a membrane-spanning region; its Gene Ontology location is reachable by antibodies, with medium confidence.
Gene: Protein-coding gene on chromosome 13 (20,221,962 to 20,232,450, reverse strand). Ensembl gene ENSG00000121742.
Subcellular location: Cell membrane; Cell junction, gap junction
Subcellular location (Human Protein Atlas): Cell Junctions
Pathways (Reactome):
Vesicle-mediated transport: Gap junction assembly
Gene Ontology:
Molecular function: actin filament binding; beta-tubulin binding; gap junction channel activity; gap junction channel activity involved in cell communication by electrical coupling; microtubule binding; protein binding
Biological process: gap junction assembly; gap junction-mediated intercellular transport; transmembrane transport; cell-cell signaling; maintenance of blood-brain barrier; sensory perception of sound; sinoatrial node development; cell communication; cell communication by electrical coupling
Cellular component: actin filament; cell junction; gap junction; connexin complex; plasma membrane
Genetic constraint (gnomAD): Loss-of-function variants: 13 observed, 13.49 expected, observed/expected ratio (o/e) 0.96, 90% interval 0.63 to 1.52. The upper end of that interval is the gene's LOEUF score, 1.52, which puts it in group 6 of 6, group 1 being the genes least tolerant of losing a copy. Missense variants: 298 observed, 343.87 expected, observed/expected ratio (o/e) 0.87, 90% interval 0.79 to 0.95. Synonymous variants: 136 observed, 137.37 expected, observed/expected ratio (o/e) 0.99, 90% interval 0.86 to 1.14.
Gene-disease validity (ClinGen):
ClinGen rates the evidence that GJB6 causes each of these diseases.
Clouston syndrome (autosomal dominant): Definitive. Clouston syndrome (or hidrotic ectodermal dysplasia) is characterized by the clinical triad of nail dystrophy, alopecia, and palmoplantar hyperkeratosis.
nonsyndromic genetic hearing loss (autosomal recessive): Refuted.
Homologues: Orthologues: dog GJB6 (98% identical), macaque GJB6 (97% identical), rabbit GJB6 (96% identical), mouse Gjb6 (95% identical), rat Gjb6 (95% identical), guinea pig GJB6 (94% identical), chimpanzee GJB6 (87% identical), pig GJB6 (82% identical), tropical clawed frog gjb2 (61% identical), zebrafish gjb8 (58% identical). Paralogues in human: GJB2 (66% identical), GJB1 (55% identical), GJB4 (44% identical), GJB5 (43% identical), GJA8 (43% identical), GJB3 (43% identical), GJA3 (42% identical), GJA1 (42% identical), GJA4 (40% identical), GJA5 (39% identical), GJA9 (39% identical), GJB7 (39% identical), and 8 more.
Diseases named in the same sentence as GJB6 in open-access papers:
GJB6 is named in the same sentence as 103 diseases in open-access papers, as found by Europe PMC text mining. Sharing a sentence is not in itself a finding about the gene and the disease. The quoted sentences say what the papers report.
hearing loss (82 papers, 2005 to 2026). "While the link between GJB2 or GJB6 variants and hearing loss is well-established, the exact role of inner ear connexins in the development of deafness remains incompletely understood." (PMID 41463117, 2025). "Patient 1 is a 22-month-old female child with severe hearing impairment due to a mutation in homozygosis of both GJB6 alleles [del(GJB6-D13S1830)]." (PMID 40504319, 2025). "One recent study showed the presence of GJB2 or GJB6 mutations in 38% of patients with non-syndromic hearing loss in Argentina." (PMID 37928735, 2023). "Other genes were related to BPD-associated outcomes such as retinopathy of prematurity (ROP, e.g., GBP3, FJX1, HIPK2) and hearing loss (e.g., GJB6, TMEM63B) and mitochondrial energy metabolism (e.g., TOMM7, SLC25A26, SLC25A33, PDK1, PKM, MDH1)." (PMID 35484630, 2022). "Pathogenic mutations in the Gjb2 and Gjb6 genes, encoding connexin 26 (Cx26) and connexin 30 (Cx30), respectively, have been linked to the most frequent monogenic hearing impairment, nonsyndromic hearing loss, and deafness DFNB1." (PMID 36016655, 2022). "It has been suggested that several mutations such as c.235delC in GJB2, A194T in GJB3, 150‐kb large deletion in GJB6 are the important causes for non‐syndromic hearing loss in many populations worldwide." (PMID 34811812, 2022). "In the organ of Corti, Cx30 is assembled into large gap junctions in the diverse cell network that supports hair cell survival, and several GJB6 gene mutations have been documented to cause hearing loss." (PMID 33735099, 2021). "Genetic variants in GJB2 and GJB6 genes are the most frequent causes of hereditary hearing loss among several deaf populations worldwide." (PMID 33096615, 2020). "Clinically, mutations and/or deletions in GJB2 (encoding Cx26) and/or GJB6 (encoding Cx30) are responsible for nearly 50% of congenitally acquired hearing loss with ~135 different mutations in GJB2 causing hearing loss." (PMID 32393745, 2020). "GJB3 (Gap Junction Protein β 3) and GJB6 (Gap Junction Protein β 6) are the next frequent genes that can cause hearing impairment but they are less common, with less than 10 mutations cited." (PMID 33333757, 2020). "GJB2 or GJB6, encoding for connexin 26 and 30, respectively, are two major deafness genes that induce a high incidence of non-syndromic hearing loss, both autosomal dominant (DFNA3) as recessive (DFNB1)." (PMID 33193034, 2020). "Nevertheless, in most African populations, GJB2 and GJB6 variants are rarely implicated in hearing impairment with some GJB2 cases found in Morocco, Sudan, and Kenya, yet an exceptionally high prevalence is found in Ghana." (PMID 32012697, 2020). "In three probands, digenic inheritance of GJB2/GJB3 and GJB2/GJB6 mutations was identified as the likely pathogenic cause for their hearing loss." (PMID 31992338, 2020). "Our study aimed to investigate GJB2 (connexin 26) and GJB6 (connexin 30) mutations associated with non-syndromic childhood hearing impairment (HI) as well as the environmental causes of HI in Ghana." (PMID 31620164, 2019). "The 46 DXN families were further classified based on consanguinity and the role of GJB2/ GJB6 mutations in the incidence of hearing loss, as the principle of complementarity cannot be applied to this subgroup at the phenotypic level." (PMID 29921236, 2018). "DFNB1, the first locus to have been associated with deafness, has two major genes GJB2 & GJB6, whose mutations have played vital role in hearing impairment across many ethnicities in the world." (PMID 29921236, 2018). "GJB6 gene mutations less contribute to the development of hearing loss but several mutations associated with HL have been described in scientific literature." (PMID 26896187, 2016). "For example, deficiency of Connexin 30 in mice causes severe hearing impairment as observed in human patients of GJB6, which is caused by mutations in CX3056." (PMID 26915689, 2016).
hearing loss (continued). "The current study evaluated the relationships between polymorphisms in the GJB2 and GJB6 genes and autosomal recessive nonsyndromic hearing loss in a sample of the Brazilian population." (PMID 26075227, 2015). "The DFNB1 locus, which contains the GJB2 and GJB6 genes, plays a key role in nonsyndromic hearing loss." (PMID 26075227, 2015). "For auditory function, the important role of intercellular communication via gap junctions has been confirmed by findings that certain CX gene mutations, particularly those of GJB2 and GJB6, cause hearing loss." (PMID 21731760, 2011). "The important role of intercellular communication, particularly that between GJB2 and GJB6 (encoding CX26 and CX30), has been confirmed by evidence that certain connexin gene mutations cause sensorineural hearing loss." (PMID 21731760, 2011). "A recent study identified a heterozygous mutation, c.119C>T (p.A40V), in the GJB6 gene of patients with nonsyndromic hearing loss." (PMID 21731760, 2011). "Dysfunctional gap junctions caused by GJB2 (CX26) and GJB6 (CX30) mutations are implicated in nearly half of nonsyndromic hearing loss cases." (PMID 21731760, 2011). "Examples of other protective variants include the N352S variant in B4GALT1 which is protective against cardiovascular disease and protein-truncating variants in GPR75 which reduce the risk of obesity, as well as the A88V variant in Gjb6, which protects against hearing loss in mice." (PMID 38011198, 2023). "Connexin 30, encoded by GJB6, also causes moderate to profound hereditary hearing loss." (PMID 36672810, 2022). "Accordingly, mutations in the human gene (GJB6) lead to skin disease and hearing loss." (PMID 33735099, 2021). "GJB2 and GJB6 mutations account for up to 50% of all nonsyndromic hearing loss cases." (PMID 35110999, 2021). "In addition, a relationship between the expression level of GJB6 and the severity of hearing loss caused by GJB2 mutations has been suggested." (PMID 34356098, 2021). "GJB6, which encodes connexin 30 (CX30), is another well-known causative gene for hearing loss." (PMID 34356098, 2021). "The GJB6 gene has been associated with Clouston syndrome and hearing impairment." (PMID 33126609, 2020). "Another example of hearing loss where multiple cell types may be affected includes Connexin 26 and 30 encoded by Gjb2 and Gjb6, respectively, which appear to be expressed in intermediate and basal cells and, to a lesser extent, marginal cells." (PMID 31920542, 2019). "Furthermore, new studies, investigating other genes, such as GJB6, must take place in order to identify the etiology of hearing loss of these patients." (PMID 29773520, 2019). "Mutations of GJB2 and GJB6, encoding Cx26 and Cx30, respectively, are associated with hearing loss." (PMID 29534490, 2018). "In addition, a missense mutation in GJB6 affecting the amino-terminal of CX30 (T5M) is associated with non-syndromic autosomal dominant (DFNA3) middle to high-frequency hearing impairment with late onset." (PMID 25381570, 2015). "Finally, we provide important evidence of the association of SNPs in the GJB2 and GJB6 genes with hearing loss." (PMID 26075227, 2015). "Other genes, such as GJB3, GJB6 and mtDNA 12SrRNA, may also play an important part in the pathogenesis of hearing loss in different countries or areas." (PMID 23554706, 2011). "A 309-kb deletion has also been reported in the GJB6 gene of hearing loss patients." (PMID 21731760, 2011). "The three most significantly associated SNPs for hearing loss are all located at the GJB2/GJB6 locus on 13q12.1, including rs870729 near GJB6 (p = 3.38×10−11, OR: 1.69), rs3751385 within GJB2 (p = 1.50×10−9, OR: 1.63), and rs7329467 within GJA3 (p = 6.87×10−8, OR: 1.68)." (PMID 20126254, 2010).
hearing loss (continued). "However, studies with the Brazilian population have shown that the screening of the GJB2 and GJB6 genes explains the etiology of hearing loss (HL) in only 1–24.7% of the subjects analyzed, being the c.35delG (rs80338939) mutation in GJB2 (NM_004004.5) gene, the most frequent pathogenic variant." (PMID 30068397, 2018). "Amongst other genetic variants, Gjb2 and Gjb6, which encode connexin 26 (Cx26) and connexin 30 (Cx30), respectively, are responsible for DFNB1, the principal cause of non-syndromic hearing loss in the Mediterranean population." (PMID 41601591, 2026). "Digenic inheritance of non-syndromic hearing loss caused by GJB2 and GJB3 or GJB6 has been described." (PMID 40121402, 2025). "Despite these advances, in Latin America, the population with hearing loss remains underdiagnosed, with most studies focusing on a single locus encompassing the GJB2/GJB6 genes." (PMID 38397168, 2024). "This study aimed to identify the genetic causes of hearing loss (HL) in a family with Iranian Azeri Turkish ethnicity negative for gap junction beta-2 (GJB2), gap junction beta-6 (GJB6), and mitochondrially encoded 12S rRNA (MT-RNR1) deleterious mutations." (PMID 35101039, 2022). "Within the over 20 pathogenic variants reported leading to ARNSHL, it is especially the large deletions in the GJB2 or GJB6 genes that lead to hearing impairment either in a homozygous, heterozygous or compound heterozygous state." (PMID 36672810, 2022). "Mutations in connexin genes—Cx26 (GJB2), Cx30 (GJB6), Cx29 (GJC3), Cx31 (GJB3) and Cx43 (GJA1)—have been identified as the culprits for hearing loss with distinct pathological changes in the cochlea." (PMID 33917368, 2021). "Almost 60% of children with profound prelingual hearing loss (HL) have a genetic determinant of deafness, most frequently two DFNB1 locus (GJB2/GJB6 genes) recessive pathogenic variants." (PMID 31952308, 2020). "After mutations in the GJB2 and GJB6 genes, mutations in SLC26A4 are considered the major cause of hereditary hearing loss in the Brazilian population and in many other populations, contributing to up to 14% of cases of moderate, profound or severe deafness." (PMID 30068397, 2018). "Mutations in the genes encoding Cx26 (GJB2) and Cx30 (GJB6) cause non-syndromic inherited deafness, and alterations in the GJB2 gene are the most common etiology of childhood hearing loss in American and European populations." (PMID 28513246, 2017). "Cx30 (GJB6), Cx29 (GJC3), Cx31 (GJB3), and Cx43 (GJA1) mutations can also cause hearing loss with distinct pathological changes in the cochlea." (PMID 26074771, 2015). "delGJB6-D13S1830 mutation is the second most frequent genetic cause of non-syndromic prelingual hearing impairment in the Spanish population and a digenic pattern of inheritance involving GJB2 mutations and delGJB6-D13S1830 mutation in GJB6 gene is sug-gested." (PMID 23503914, 2013). "Approximately 50% of autosomal recessive nonsyndromic hearing loss can be attributed to the disorder DFNB1, caused by mutations in GJB2 (which encodes the protein connexin 26) and GJB6 (which encodes the protein connexin 30)." (PMID 23648117, 2013). "We also considered the mutations in the GJB2, GJB6 and SLC26A4 genes which are recognised to be among the most frequent causes of hearing impairment." (PMID 23969527, 2013). "In this study, we screened the GJB2, GJB3, GJB6, SLC26A4, SLC26A5 IVS2-2A>G and mitochondrial genes to determine the etiology of hearing loss in eastern China." (PMID 23554706, 2011). "After the systematic comparison of various genes in different countries or ethnic differences between the mutation frequencies, we calculated the average frequency of GJB2, GJB3, GJB6, SLC26A4 and mtDNA mutations in patients with nonsyndromic hearing loss." (PMID 23554706, 2011). "Mutations in three connexin encoding genes, GJB2 (Cx 26), GJB6 (Cx 30), and GJB3 (Cx 31) have been found to cause hearing loss." (PMID 20835527, 2010).
hearing loss (continued). "Mutations in three connexin (Cx) genes, GJB2 (Cx26), GJB6 (Cx30), and GJB3 (Cx31), have been identified and are known to cause hearing impairment." (PMID 19366456, 2009). "Ten patients with a family history of hearing loss showed mutations in GJB2, GJB3, GJB6, SLC26A4, mtDNA 12S rRNA, or mtDNA tRNAser(UCN) in our study population." (PMID 19744334, 2009). "Patient 3 is a 48-year-old man with neurosensory deafness caused by a mutation in the compound heterozygosity of GJB6 [del(GJB6-D13S1830) and del(GJB6-D13S1854)] who had been studied in 2009 after having had twins with hearing impairment (cases 7–8) due to a GJB6 mutation in heterozygosity." (PMID 40504319, 2025). "In addition, it has been described that non-syndromic hearing loss is more frequently autosomal recessive, where approximately 50% involve the DFNB1 locus, caused by variants in the GJB2 and GJB6 genes." (PMID 41254778, 2025). "Recent decisions by the ClinGen Hearing Loss Expert Panel further refute any association of GJB6 with nonsyndromic hearing loss." (PMID 40225913, 2024). "Mutations in GJB6, which encodes Cx30, have also been associated with the development of comprehensive or non-comprehensive hereditary hearing loss." (PMID 37373495, 2023). "To see whether nuclear genes (GJB2, GJB3, GJB6, and TRMU) mutations played active roles in clinical expression of hearing impairment, we initiated a mutational analysis of the exons of GJB2, GJB3, GJB6, and TRMU in matrilineal relatives of this pedigree." (PMID 34811812, 2022). "This study aimed to investigate GJB2 (MIM: 121011) and GJB6 (MIM: 604418) variants associated with familial non-syndromic hearing impairment (HI) in Senegal." (PMID 35625523, 2022). "Mutations in Gja1 (Cx43), Gjb2 (Cx26), Gjb3 (Cx31), and Gjb6 (Cx30), which constitute gap junctions, can cause non-syndromic hearing loss." (PMID 34199197, 2021). "Furthermore, mutations in GJB2, GJB3, GJB6 and TRMU were implicated to be associated with hearing impairment." (PMID 32400865, 2020). "This study aimed to investigate GJB2 (connexin 26) and GJB6 (connexin 30) mutations associated with familial non-syndromic childhood hearing impairment (HI) in Cameroon." (PMID 31731535, 2019). "For the first time, we analyzed the informative parameters of nine predictive in silico tools, obtained by predictions of the clinical significance of missense variants of GJB2 (Cx26), GJB6 (Cx30), and GJB3 (Cx31) connexin genes associated with hearing impairment." (PMID 31015822, 2019). "We and others have reported 223 different mutations in GJB2 and GJB6 associated with hearing impairment but not with skin abnormalities in Argentina." (PMID 27141831, 2016). "The importance of gap junctional communication for auditory function has been highlighted by the discoveries that mutations in GJB2 (coding for CX26), GJB6 (CX30) and GJB3 (CX31) may all cause hereditary hearing loss." (PMID 25381570, 2015). "Three large deletions have also been characterized thus far, involving part of the GJB6 gene and the associated chromosomal downstream region, which also lead to serious non-syndromal hearing impairment." (PMID 24551843, 2014). "High-resolution genome-wide CNV analysis of 150 cases and 157 controls revealed deletions in genes known to be involved in hearing (e.g. GJB6, OTOA, and STRC, encoding connexin 30, otoancorin, and stereocilin, respectively), supporting CNV contributions to hearing loss phenotypes." (PMID 25528277, 2014). "Although our initial aim was to evaluate the effect of GJB2 and GJB6 mutations on the outcome of CI in children with congenital hearing loss, our patient population appeared to have no GJB6 mutation." (PMID 22567367, 2011). "It is as yet unclear how, exactly, a lack of transcription results in a hearing loss phenotype and to what extent partial or complete deletion of the GJB6 gene contributes to this phenotype in humans." (PMID 21738759, 2011).